SDC2 (syndecan 2)
Diseases named in the same sentence as SDC2 in open-access papers (continued):
Sharing a sentence is not in itself a finding about the gene and the disease.
breast carcinoma (continued). "The increased levels of SDC2 after E2 treatment may be connected with the ability of SDC2 to modulate the tumorigenic and invasive behavior of breast cancer cells." (PMID 25140302, 2014). "SDC2 mRNA expression was notably downregulated in breast carcinoma tissues stratified by nodal metastasis status (N0, N1, N2, and N3), which aligned with our qPCR results in breast cancer tissue samples and staging (I, II, III, and IV) relative to normal tissues." (PMID 40940401, 2025). "Constitutive and induced expression of SDC2 and 4 are affected by the coordinated crosstalk between the RTK EGFR and IGFR with ERs in vitro in MCF-7 and ERβ-positive MDA-MB-231 breast cancer cells." (PMID 36980680, 2023). "Our results showed that MV-enriched EVs isolated from obese breast cancer patients with pLNM contained higher SDC2, but not SDC1 and SDC4, compared to those with nLNM." (PMID 40940401, 2025). "Despite a lack of information regarding the association of SDC2 and the EMT in breast cancer, SDC2 emerges as a promising candidate with a relevant function in this context since its expression seems to be higher in mesenchymal than epithelial tissues." (PMID 36980680, 2023). "We report that Syndecan‐2 (SDC2) is expressed on a nonepithelial, nonhaematopoietic, nonendothelial stromal cell population within breast cancer tissue." (PMID 33152121, 2021). "Our patient tissue microarray data showed that syndecan-2 expression and caveolin-2 were significantly increased in breast cancer patients regardless of tumor grade." (PMID 25623282, 2015). "Thus, a new generation of bisphosphonate, zoledronate (zoledronic acid, Zometa), downregulates the expression levels of SDC1, SDC2, and GPC1 and upregulates the expression of SDC4 in breast cancer cells of low and high metastatic capability." (PMID 25140302, 2014). "In our previous study, we demonstrated that estradiol does not affect the levels of syndecan-4 in breast cancer cells through ERα signaling although the levels of syndecan-2 are regulated by hormonal treatment." (PMID 23844358, 2013). "In an orthotopic immunocompromised breast cancer model, overexpression of syndecan‐2 in TASCs significantly enhanced TGFβ signalling (SMAD7, PAI‐1), tumour growth and metastasis, whereas reducing levels of SDC2 in TASCs attenuated TGFβ signalling (SMAD7, PAI‐1, CXCR4), tumour growth and metastasis." (PMID 33152121, 2021). "This study aimed to examine the expression patterns of SDC1, SDC2, and SDC4 in EVs isolated from peripheral blood of neoadjuvant chemotherapy-naïve obese breast cancer patients with negative LNM (nLNM) and positive LNM (pLNM) to discover their potential as new biomarkers for LNM." (PMID 40940401, 2025).
adenoma (15 papers, 2014 to 2026). A neoplasm arising from the epithelium. "The combined detection of TFPI2 and SDC2 showed both high specificity and sensitivity, especially for cancer and adenomas in the left colon for both tissue and stool specimens." (PMID 35004840, 2021). "SDC2/TFPI2-combined detection showed higher sensitivity not only to cancer samples but also to adenoma samples." (PMID 35004840, 2021). "SDC2/TFPI2-combined detection showed better diagnostic performance than SDC2 detection alone for CRC vs. normal and for adenoma vs. normal as well as for adenoma vs. CRC." (PMID 35004840, 2021). "We further checked the performance when combining methylated SEPT9, NDRG4, and SDC2 for detecting adenoma and CRC." (PMID 31602277, 2019). "In this study, we applied LTE-qMSP assay to measure SDC2 methylation status in stool DNA from 50 CRCs, 21 adenomas, and 22 healthy individuals." (PMID 29225717, 2017). "When ML values were used as the detection index in ROC curve analysis, SDC2/TFPI2-combined detection also showed better diagnostic performance than SDC2 detection in discrimination between cancer and normal, between adenoma and normal, and between adenoma and cancer." (PMID 35004840, 2021). "TFPI2 can improve the sensitivity of SDC2 methylation–specific detection of colorectal tumorous lesions while maintaining high specificity, in particular reducing the missed detection of left colon cancer and adenoma." (PMID 35004840, 2021). "BMP3, NDRG4, and SDC2 showed a significantly higher methylation level in CRC than adenoma samples." (PMID 31602277, 2019). "In a previous study, the detection rate of SDC2 methylation was 81.1 and 58.2% for CRC and adenoma, respectively, with the specificity of 93.3%, which was in agreement with our study and other research studies, indicating that the sensitivity of SDC2 for CRC and adenoma had room to be improved." (PMID 35004840, 2021). "Another DNA methylation study specifically evaluated methylation in four genes (SFRP1, SFRP2, SDC2 and PRIMA1), with an AUC of 0.93 for the multi-marker panel for detecting adenoma." (PMID 34503217, 2021). "The AUC value of SDC2/TFPI2 for CRC vs. adenoma was 0.72, with the specificity of 64.20% and sensitivity of 73.80%, which was lower than that of CRC vs. normal or adenoma vs. normal." (PMID 35004840, 2021). "All these results indicated that the combination of SEPT9, NDRG4, and SDC2 methylation levels was sufficient for effective detection of CRC and adenoma." (PMID 31602277, 2019). "Methylation of SEPT9, NDRG4 and SDC2 combined has high feasibility for detecting CRC and adenoma, with better performance for detecting CRC over adenoma." (PMID 31602277, 2019). "meSDC2 LTE-qMSP test showed higher frequency and higher level of aberrant SDC2 methylation in both CRC and adenomas patients than that in subjects with NED." (PMID 30876480, 2019). "A study based on Chinese fecal samples showed that SDC2 methylation testing had a sensitivity of 81.1% for CRC and a detection rate of 58% for advanced adenomas, leading to missed diagnoses of left-sided colon cancer and adenomas." (PMID 38542332, 2024). "Furthermore, the combination of methylated SEPT9, NDRG4, and SDC2 showed high feasibility of detection of CRC and adenoma and further study showed better performance in detecting CRC than adenoma." (PMID 31602277, 2019). "Our results demonstrate that abnormal SDC2 methylation is a frequent event in precancerous adenomas and CRC but is negative in normal mucosa." (PMID 29225717, 2017). "When the SDC2/TFPI2-combined PCR assay was performed in stool specimens, the AUC value of cancer vs. control was 0.98, with the specificity of 96.40% and sensitivity of 96.60%, and the AUC value of adenoma vs. control was 0.87, with the specificity of 95.70% and the sensitivity of 80.00%." (PMID 35004840, 2021).
adenoma (continued). "In our study, the methylation level of CRC and adenoma was statistically different in stool samples; however, SDC2/TFPI2 did not differentiate CRC and adenoma well enough, which meant that the methylation pattern of adenoma was more similar to that of CRC." (PMID 35004840, 2021). "Although methylated markers such as RASSF1A, SDC2, BCAT1, IKZF1, ALX4, SDC2 and WIF-1, among others, have demonstrated some usefulness for the detection of established cancers, the goal of detecting precancerous adenomas has not been achieved yet." (PMID 32605302, 2020). "Furthermore, a 4-biomarker panel was the only one combining methylated BMP3, NDRG4, SDC2 with FOBT (and not FIT), achieving a moderately good performance for detection of CRC, 85.4% sensitivity and 92% specificity, and all adenomas (85.7% sensitivity)." (PMID 40402271, 2025).
melanoma (14 papers, 2011 to 2025). A malignant, usually aggressive tumor composed of atypical, neoplastic melanocytes. "Overexpression of Syndecan-2, which is also associated with the increased expression of collagens through integrin pathways and improves cell migration as described in melanoma cells." (PMID 37048083, 2023). "It has been reported a correlation between SDC2 and enhanced migration and progression in several types of tumors, such as fibrosarcoma, melanoma and pancreatic cancer." (PMID 40940401, 2025). "Another syndecan, SDC2, together with PTPRJ is on top of the R-L-list in the melanocytic module and plays a crucial role in the migratory potential of melanoma cells and metastatic melanoma associated with cachexia, respectively." (PMID 38785552, 2024). "SDC3 is specifically increased in melanoma and brain tumors, but SDC2 and GPC3 are up-regulated in HCC." (PMID 35850748, 2022). "Detachment stress also affected the chemosensitivity of melanoma cells through upregulation of syndecan-2-mediated ERK/PI3K activation." (PMID 35802540, 2022). "SDC2 expression is upregulated in breast, colon, and pancreatic cancers, and melanomas, whereas high levels of SDC2 in neuroendocrine tumors correlate with a better survival of patients." (PMID 32916872, 2020). "PI3 kinase-AKT and ERK activation is reported to characterize melanoma cells upon anchorage independency and syndecan 2 (SDC2) increased expression." (PMID 31275384, 2019). "In this study, we suggested SDC2 overexpression would enhance cell migration, however, suspended melanoma cells with higher SDC2 expression showed characteristics of invasiveness loss." (PMID 28977882, 2017). "In this paper, we characterized the upregulation of SDC2 in melanoma cells and investigated their functional role in cell migration, signaling, and chemosensitivity." (PMID 28977882, 2017). "Overexpression of SDC2 protein increased cell mobility while suppression of SDC2 expression decreased cell mobility at either adherent melanoma or suspended melanoma cells as investigated by transwell cell migration assay." (PMID 28977882, 2017). "This suggested that SDC2 protein specifically enhanced chemosensitization in suspended melanoma cells." (PMID 28977882, 2017). "Syndecan-2 (SDC2) had been shown to be associated with increased migration and invasion of melanoma cells and melanin synthesis." (PMID 28977882, 2017). "Downregulation of syndecan-1 and upregulation of syndecan-2 in melanoma A375 cells were observed by different suspension conditions." (PMID 28977882, 2017). "In conclusion, we showed upregulation of syndecan-2 in anoikis-resistant melanoma cells enhanced chemosensitivity through PI3K and ERK activation." (PMID 28977882, 2017). "We also examined whether the increased SDC2 expression in suspended melanoma cells was also mediated by PKCδ activation." (PMID 28977882, 2017). "In addition, suspended melanoma cells were more sensitive to chemoagents, which correlated with syndecan-2 overexpression, PI3K and ERK activations, serum level, and the presence of glycosaminoglycans." (PMID 28977882, 2017). "Upregulation of SDC2 in melanoma cells under anchorage independency enabled higher sensitivity to lower dose of chemoagents, which might prevent spreading of malignant melanoma under suspension." (PMID 28977882, 2017). "Since SDC2 expression were upregulated in anoikis-resistant melanoma cells upon suspension, we examined whether increased chemosensitization was also presented." (PMID 28977882, 2017). "The expression of SDC1 and SDC2 in different melanoma cells were examined." (PMID 28977882, 2017). "The increase of SDC2 expression was more significant in melanoma A375 cells." (PMID 28977882, 2017). "Interestingly, it was recently reported that overexpression of syndecan-2 enhanced the migration and invasion of melanoma cells." (PMID 21731601, 2011).
melanoma (continued). "Since enhanced chemosensitivity in the presence of serum was achieved by elevated SDC2 expression and pathway activation upon cell detachment, applications of specific chemoagents against melanoma in lower dosage would be effective to kill suspended melanoma cells." (PMID 28977882, 2017). "The integrin-dependent focal adhesion kinase (FAK) regulates SDC2 induced tumorigenic activity of HT1080 fibrosarcoma and melanoma cells." (PMID 32916872, 2020). "For suspended melanoma cells, SDC2 overexpression increased the amount of cleaved PARP, while suppression of SDC2 expression decreased the amount of cleaved PARP." (PMID 28977882, 2017). "In contrast, SDC2 expression in suspended melanoma cells was suppressed by PKCδ inhibitor, but not by PKCα/β inhibitor." (PMID 28977882, 2017). "While our IPA analysis did not include the category of melanoma cell migration, RNA-Seq indicated that SDC2 and VCAN might have led to the motility." (PMID 31988291, 2020). "PKCα/β inhibitor, but not PKCδ inhibitor, reduced SDC2 expression in adherent melanoma cells." (PMID 28977882, 2017).
gastric cancer (12 papers, 2016 to 2025). A primary or metastatic malignant neoplasm involving the stomach. "The results showed that CD79A, DERL3, TNFRSF17, FKBP11, VSIR, SDC2, and other genes play vital regulatory roles in the formation of gastric cancer." (PMID 39391750, 2025). "Some studies have shown that the hypermethylation of SDC2 is found in some malignant tumor tissues, such as the hypermethylation of SDC2 can be detected in gastric cancer tissues, and it can also be seen in head and neck squamous cell carcinoma." (PMID 35754025, 2022). "According to the discussion above, we considered that SV2B and SDC2 deserved to be further studied in gastric cancer." (PMID 33178362, 2020). "SDC2 methylation level has been found to elevate in tumor tissues of some types of cancers such as glioma and gastric cancer." (PMID 33126908, 2020). "The methylation of XKR6, CCDC57, MAML3, SDC2, and CLIP4 is associated with age and tumor location in gastric cancer." (PMID 33575272, 2020). "Meanwhile, MethHC database revealed that SDC2 was frequently methylated in tissues from colorectal and gastric cancers, but less frequently or unmethylated in most of the other solid tumors or normal tissues from patients of European continental origin." (PMID 30876480, 2019). "A frequent SDC2 hypermethylation was in tissues of gastric cancer, and aberrant methylation of SDC2 was correlated with diffuse-type and mixed-type gastric cancers." (PMID 29225717, 2017). "The proteoglycans syndecan-1, syndecan-2, syndecan-4, glypican-1 and glypican-3 were upregulated in gastric cancer with high in vitro and in vivo peritoneal seeding potential, suggesting a role for these molecules in peritoneal dissemination." (PMID 27074785, 2016). "As for SV2B and SDC2, encoding a member of the synaptic vesicle protein 2 and syndecan 2, respectively, both of them have not been fully studied in gastric cancer." (PMID 33178362, 2020). "Therefore, we included gastric cancer patients to determine whether SDC2 methylation was detectable in stool samples from gastric patients." (PMID 30876480, 2019). "We subsequently found numerous DEGs related to macrophages related to the development of gastric cancer, such as CST3, MS4A6A, CTSS, MPEG1, VSIR, and SDC2." (PMID 39391750, 2025). "An immunohistochemical (IHC) investigation assessed the expression levels of hub genes (SDC2, RGS4, SERPINE1, DUSP1, and CAV1) in gastric cancer." (PMID 39871942, 2024). "Furthermore, we analyzed the genes related to the differential expression of neutrophils during the development of gastric cancer, for instance, CXCR2, CMTM2, FCGR3B, CXCR1, SDC2, and FABP5." (PMID 39391750, 2025). "The results showed that the methylation of SDC2, SFRP2, TERT, and RASSF2 has a certain sensitivity and high specificity in GC screening, which is a potential fecal biomarker of gastric cancer." (PMID 35309131, 2022).
glioma (12 papers, 2014 to 2025). A benign or malignant brain and spinal cord tumor that arises from glial cells (astrocytes, oligodendrocytes, ependymal cells). "Syndecan-2 (SDC2) is expressed in the microvasculature of gliomas and regulates angiogenic processes in microvascular endothelial cells." (PMID 35614104, 2022). "In our study, we found that the expression of VCAM1, ICAM1, CDH2 was down-regulated, while the expression of SDC2 was up-regulated after knocking down the expression of GNG5 in glioma cells." (PMID 34098960, 2021). "Proangiogenic factors were found to stimulate the shedding of syndecan-2 during glioma tumorigenesis, and shed syndecan-2 was found to promote angiogenic processes." (PMID 25686828, 2015). "SDC2 is highly expressed in glioma microvasculature regulating angiogenesis." (PMID 37189838, 2023). "MES-like glioma cells expressed multiple receptors for ANGPTL4, including syndecans SDC2, SDC3, and SDC4 as well as WNT5A receptor FZD6, suggesting that these pathways may be responsible for the enrichment of GSCs in ECMhi tumors." (PMID 37292803, 2023). "We found that decreasing the expression level of GNG5 in glioma cells could significantly affect the expression of VCAM1, ICAM1, CDH2, and SDC2, which are key molecules of cell adhesion molecules." (PMID 34098960, 2021). "Heparan sulfate proteoglycans (HSPGs) family member—syndecan-2 (SDC2), a membrane-anchored proteoglycan, was found to be expressed on high levels in brain tumor tissues, including gliomas, whereas never found in NSCs." (PMID 31803736, 2019). "In comparison to the grade III sample, ECM-affiliated genes (COLEC12, SDC2 and SEMA5A) showed enhanced spatial expression in GBM regions with perivascular microgliosis associated with pseudopalisading necrosis, that are largely absent in lower-grade gliomas." (PMID 41366031, 2025).
lung carcinoma (10 papers, 2008 to 2025). "Syndecan-2 is thought to be an important factor in normal development and its abnormal expression has been associated with colon and lung cancers, where it is found to facilitate metastasis by increasing motility and promoting angiogenesis." (PMID 22583667, 2012). "In lung cancer, SDC‐2 deficiency prevents cells from adhering to FN, which blocks their migration." (PMID 35702951, 2022). "A number of classifier genes that regulate cell growth and proliferation are up-regulated in patients with lung cancer, including SDC2, and NKX3-1 as well as the cell-cycle-arrest mediator CGREF1." (PMID 25944280, 2015). "Similar cooperation was found by silencing techniques between syndecan-2 and -4 in actin stress fibre formation in lung cancer cell lines P29 and LM66-H11, or between syndecan-1 and syndecan-4 in the migration of dendritic cells after their phospholipid induced maturation." (PMID 22745764, 2012). "Similarly, syndecan-2 was noted to promote focal adhesion formation in Lewis-lung carcinoma cells, and syndecan-2 and syndecan-3 induce filopodia formation in COS-1, CHO-K1, Swiss 3T3, and dendritic cells." (PMID 18545691, 2008). "SDC2 also suppresses MMP-2 activation, and subsequently metastasis, of lung carcinoma cells." (PMID 22900087, 2012).